SYP (synaptophysin)
Diseases named in the same sentence as SYP in open-access papers (continued):
Sharing a sentence is not in itself a finding about the gene and the disease.
carcinoid (continued). "In contrast to typical appendiceal carcinoids which stain more homogenously positive for CgA and synaptophysin, GCCs often show a more scattered positivity of the neuroendocrine markers." (PMID 25671432, 2015). "Typical and atypical carcinoids are characterized by a tumor size >5 mm with carcinoid morphology and immunohistochemical expression of the cell markers chromogranin A and synaptophysin." (PMID 26798346, 2015). "Immunohistochemistry of the duodenal biopsy was positive for synaptophysin and chromogranin-A; consistent with the diagnosis of stage I carcinoid tumor." (PMID 29147314, 2012). "His cells were positive for chromogranin A and synaptophysin, and a diagnosis of "typical" carcinoid of the gallbladder was made." (PMID 21801379, 2011). "Immunohistochemically, synaptophysin, chromogranin and neuron specific enolase were the most valuable markers for the diagnosis of primary carcinoid tumor arising within mature teratoma of the kidney, as in the case herein presented." (PMID 19523243, 2009). "Immunohistochemically, synaptophysin, chromogranin and neuron specific enolase were the most valuable markers for the diagnosis of primary carcinoid tumor arising within mature teratoma of the kidney." (PMID 17509135, 2007). "Subsequent investigations, including immunohistochemical and ultrastructural studies, proposed a unified origin, showing co-expression of thyroid markers (such as TTF-1 and thyroglobulin) and neuroendocrine markers (synaptophysin, chromogranin-A) in the carcinoid areas or transitional zones." (PMID 40428242, 2025). "Carcinoid tumors stain positively for keratin 18, chromogranin A, and synaptophysin." (PMID 23691399, 2013). "The other immunohistochemical markers that were positive in all the carcinoid tumors in which they were used were Synaptophysin (100%; 3/3), Neuron specific enolase (100%; 3/3), Serotonin (100%; 2/2), CD 56 (100%; 1/1), Thyroxine (100%; 1/1), Glucagon (100%; 1/1), and Somatostatin (100%; 1/1)." (PMID 17509135, 2007). "Immunoreactivity for chromogranin A, synaptophysin, TTF-1, and pan-cytokeratins AE1–3 was documented in carcinoid component, while adenocarcinomatous component was positive only for TTF-1 and cytokeratins." (PMID 34926584, 2021). "With NE morphology, or suspected NE morphology, it would be possible to diagnose HGNET or carcinoid using a combination of classic NE markers (CD56, synaptophysin, and chromogranin A) and Ki-67." (PMID 34829292, 2021). "Tumor cells revealed immunoreactivity for the neuroendocrine markers following NSE, synaptophysin, and CD56, and these findings are typical of carcinoid tumors." (PMID 27098182, 2016). "Carcinoid tumors with clear or eosinophilic cell components usually stain positive for chromogranin A, synaptophysin, and CD56, while ACC stains negative for these markers." (PMID 36820581, 2023). "Immunoreactivity for chromogranin A, synaptophysin, TTF-1, and pan-cytokeratins (AE1-3 clone) was observed in carcinoid component, while glandular component was positive only for TTF-1 and cytokeratins; cytokeratin 7 was selectively expressed in the adenocarcinomatous component." (PMID 34926584, 2021). "In 2013, the patient was diagnosed with a 15 × 15 mm atypical carcinoid in the left lung that stained positive for chromogranin and synaptophysin and negative for serotonin." (PMID 26798346, 2015). "The renal masses were negative for TTF-1, napsin, chromogranin, and synaptophysin and had no histological appearance of carcinoids." (PMID 26609460, 2015). "Carcinoids are often confused with glomus tumors since they have a similar morphology, although by immunostaining carcinoids, but not glomus tumors, are positive for cytokeratin and neuroendocrine markers such as chromogranin A and synaptophysin." (PMID 23050181, 2012).
carcinoid (continued). "The carcinoid tumor component was strongly and diffusely immunoreactive (3+, cytoplasmic staining) for CD56, chromogranin and synaptophysin; weakly and focally immunoreactive (1+, cytoplasmic staining) for pancytokeratin; and negative for CA-IX, CD99, CDX2, CK7, CK20 and SMA." (PMID 19523243, 2009). "However, carcinoid, but not glomus, tumors are positive for cytokeratin and neuroendocrine markers such as chromogranin A and synaptophysin." (PMID 24386948, 2014). "Carcinoid tumors stain for synaptophysin and chromogranin, but not CK20." (PMID 15550173, 2004). "In contrast, the carcinoid was focally interspersed positive for TTF-1, patchy positive for CDX-2 and PAX-8, and CD56 (basal and cytoplasmic), strongly positive for synaptophysin, and negative for GATA-3, calretinin, and chromogranin-A." (PMID 40428242, 2025). "Carcinoids often express neurosecretory markers, including neuron specific enolase, CD56, chromogranin A and synaptophysin, whereas ACCs do not express such biomarkers." (PMID 25013491, 2014). "The carcinoid tumor component was strongly positive for CD56, chromogranin and synaptophysin, weakly positive for pancytokeratin, and negative for carbonic anhydrase IX, CD99, CDX2, cytokeratin 7, cytokeratin 20 and smooth muscle actin." (PMID 19523243, 2009). "Whitish/brownish lobulated tumors corresponded to typical carcinoids (less than 2 mitoses/2 mm2 and without necrosis); polygonal/elongated cells under lobular pattern expressed CD56, chromogranin A, synaptophysin, and CK7; Ki-67 positivity was between 1 and 3%." (PMID 26613062, 2015).
cognitive decline (36 papers, 2010 to 2026). "As synapse loss strongly correlates with cognitive decline in AD, we stained mouse brain sections with antibodies against synaptophysin (a presynaptic marker) and post-synaptic density 95 (PSD95: a postsynaptic marker)." (PMID 36104602, 2022). "The cognitive decline observed in aging mice is associated with decreased synaptic markers, as shown by decreased transcriptional expression of SYP and PSD95 with age." (PMID 31980673, 2020). "A previous study also suggested that the loss of the presynaptic vesicle protein synaptophysin (SYP) in the hippocampus correlates with cognitive decline in human patients." (PMID 31281225, 2019). "Previous studies in animal models have revealed that the loss of synaptophysin or PSD-95 in the cortex results in cognitive decline and behavioral deficits." (PMID 27009068, 2016). "Decreased expression of synaptophysin associated with cognitive decline has been described in the adult rat brain in a model of chronic induced neuroinflammation." (PMID 24524910, 2014). "Early loss of synaptic contacts has been associated with the initiation of cognitive decline, followed by neuritic damage, and neuronal cell loss, with loss of hippocampal synaptophysin correlating with cognitive decline in AD." (PMID 23418567, 2013). "There is a 24% increase in the associated pre-synaptic vesicle protein, synaptophysin, which indicates synaptic plasticity, regulates short and long term memory and correlates with cognitive decline in AD." (PMID 23071606, 2012). "Furthermore, our results also align with the overall synaptic loss seen in AD patient’s brains, where lower levels of synaptophysin in the hippocampus have been reported to correlate with cognitive decline in AD." (PMID 38902659, 2024). "Moreover, cognitive decline is relevant to the impairment of SYP in HPC and other associated cortices." (PMID 37465679, 2023). "We have also shown reduced synaptophysin levels in the irradiated brains coincident with cognitive decline." (PMID 40313772, 2025). "We have also shown reduced synaptophysin levels in the irradiated brains coincides with cognitive decline." (PMID 40605058, 2025). "Compared with those of AD patients with dementia, the levels of synaptic proteins such as synaptophysin and synaptopodin were also shown to be preserved in the brains of female subjects who presented with AD pathology but were resilient to cognitive decline." (PMID 32390822, 2020). "Both synaptophysin (SYP) and post-synaptic density protein-95 (PSD-95) are particularly vulnerable to the toxic effects of Αβ, and their loss correlates with cognitive decline in AD." (PMID 26526066, 2015). "Losses of the pre-synaptic vesicle protein synaptophysin have been shown to correlate with cognitive decline in AD cases." (PMID 23418567, 2013). "In addition to this, we also checked the level of presynaptic protein, i.e., synaptophysin, within the PsEVs, as the level of synaptophysin correlates with cognitive decline in AD." (PMID 38902659, 2024). "In addition, VX-765 has been reported to attenuate cognitive decline and brain inflammation and enhance synaptophysin protein levels in the AD mouse hippocampus." (PMID 36441377, 2022). "The high cholesterol diet did not exacerbate age-dependent cognitive decline and hippocampal neuronal death, and even greatly mitigated decreases of synaptophysin and growth associated protein 43 expression in the hippocampus of aged mice." (PMID 29896426, 2018). "The observed downregulated synaptophysin levels in AD PsEVs compared to MCI and control subjects shed light on the combined role of neuroinflammation and proteinopathy in the cognitive decline observed as the disease progresses." (PMID 38902659, 2024).
cognitive decline (continued). "BPA prenatal exposure was also reported to decrease synaptic plasticity and the gene and protein expression of NDMAR1, SYP, SPN, and PSD95, pointing out the ability of BPA to rule their expression, leading to alterations in dendritic spines and the induction of cognitive decline." (PMID 37372067, 2023). "The results show that synaptophysin and PSD95 regulation changes might have contributed to the motor and cognitive decline after ICH." (PMID 37190062, 2023). "For instance, surgical trauma could activate the hippocampal complement C3, causing a decrease in the expression of pre- and post-synaptic proteins SYP and PSD-95, which contributed to cognitive decline." (PMID 35370607, 2022). "The increased percentages of synaptophysin-bearing MVs found in this study were not linked to MMSE performance and thus a state of cognitive decline." (PMID 34295239, 2021). "Furthermore, a decrease in the expression of synaptic proteins such as synaptophysin and BDNF may contribute to reduced hippocampal synaptic plasticity with age, exacerbating cognitive decline (Bettio, Rajendran, and Gil‐Mohapel 2017)." (PMID 39816485, 2025). "Thus, aiming to investigate whether the protection against the cognitive decline observed in APP/PS1EpoD mice was due to a synaptic/axonal preservation, we analyzed the expression of synaptophysin (Syn) and PSD95, classic presynaptic and postsynaptic markers respectively." (PMID 32901091, 2020). "The role of synaptophysin in cognition is supported by reduced NOR and spatial learning and memory performance in synaptophysin null mice and a correlation between lower hippocampal synaptophysin levels and cognitive decline in AD." (PMID 36220815, 2022).
melanoma (31 papers, 2005 to 2025). A malignant, usually aggressive tumor composed of atypical, neoplastic melanocytes. "Combination-ICI treatment to intact or melanoma-bearing mice and melanoma burden itself led to a significant decline in the pre-synaptic protein, synaptophysin, at two months post-ICI treatment." (PMID 40313772, 2025). "SYP also shows ectopic or aberrant expression in adenocarcinomas of various origins, including malignant melanomas or sarcomas." (PMID 39937015, 2025). "In our patient, an accurate diagnosis was made due to the presence of IHC markers such as HMB-45, MELAN-A, and S-100, which indicate melanoma; synaptophysin and vimentin, which indicate neuroendocrine origin; and pan-CK and CK20, which ruled out carcinoma." (PMID 39624501, 2024). "Although synaptophysin is an excellent neuroendocrine marker, it has been reported to be positive in other conditions such as malignant melanoma, angiosarcoma, and classical Hodgkin lymphoma." (PMID 39439633, 2024). "However, the tumor cells were negative for NFP (neurofilament protein), CD34, desmin, actin, chromogranin, synaptophysin, and pan-melanoma." (PMID 23320233, 2012). "Both Melanoma + Veh and Melanoma + Combi-ICI-treated mice showed a significant decline in the hippocampal synaptophysin immunoreactivity and, therefore, pre-synaptic density in the CA1 SR layers and the DG ML layers." (PMID 40313772, 2025). "We retrospectively analyzed the expression of chromogranin A (CgA), synaptophysin (Syn) and CD56 as neuroendocrine markers in 308 cases with melanomas." (PMID 34454530, 2021). "Synaptophysin expression was also relatively common in EWS (on average 23%) and melanoma (on average 35%), while in SFT, chordoma, and the pancreatic SEMN, synaptophysin expression seems to be rare." (PMID 34350470, 2021). "Immunomarkers, such as chromogranian and synaptophysin, Melan A and HMB45 or desmin and smooth muscle actin, are applied to differentiate neuroendocrine, melanoma and smooth muscle tumors, respectively." (PMID 32867094, 2020). "In differentiation-supported conditions, TAFH RNAi-treated melanoma cells started to express chondrogenic-specific SOX9, NKX3.2 and RUNX2; adipogenic PPARG; and neurogenic NTRK2, NF-M and SYP mRNAs at 48 h post-stimulation of differentiation." (PMID 27499390, 2016). "Scrapings from a pathological hip fracture 3 months later revealed focal synaptophysin immunoreactivity and widespread melanoma antigen, human melanoma black 45, and SOX10 positivity, which are indicative of metastatic malignant melanoma with focal neuroendocrine differentiation." (PMID 32234068, 2020). "The tumor cells were positive for AE1/AE3, S-100 protein, melan A, HMB-45, synaptophysin, calcitonin, chromogranin A, melanoma, and thyroid transcription factor-1 (TTF-1) and negative for thyroglobulin." (PMID 30424779, 2018). "Reninomas are negative for S100 protein, HMB-45 (melanoma and angiomyolipoma markers), chromogranin, synaptophysin (neuroendocrine markers), and cytokeratin (a pan-epithelial marker more specific for RCC)." (PMID 25177679, 2014). "In melanoma, the cells are not stained with chromogranin or synaptophysin, and neither is there positivity for catecholamines, enolase and opioid peptides, which are typical pheochromocytoma markers." (PMID 21722390, 2011). "Immunohistochemical staining and electron microscopy can help differentiate the two: pigmented pheochromocytomas typically express neuroendocrine markers (e.g., synaptophysin and chromogranin) and contain neurosecretory granules, which are absent in malignant melanoma." (PMID 40896437, 2025). "Immunohistochemistry typically shows positive staining for neuron-specific enolase (NSE), synaptophysin, chromogranin, ISNM-1, CD56, neurofilament protein (NP), and negative staining for markers of epithelial malignancies, melanoma, lymphoma, or Ewing sarcoma." (PMID 39650873, 2024).
melanoma (continued). "Synaptophysin and chromogranin were utilized to rule out neuroendocrine malignancy, similarly HNM-45 for melanoma and CD-68 for undifferentiated sarcoma." (PMID 39588415, 2024). "An autopsy revealed multiple organ tumors (brain, duodenum, stomach, liver, and bile duct) negative for melanoma markers but positive for neuroendocrine markers (CD56, synaptophysin, and chromogranin A)." (PMID 39192931, 2024). "Other tumors on the differential, metastatic lung cancer, mesothelioma, melanoma, and primary adrenal gland tumor, were excluded by negative staining of tumor cells for TTF-1, napsin, calretinin, WT-1, pan-melanoma, SOX10, and synaptophysin." (PMID 32983683, 2020). "However, these tumors were also completely negative for melanoma markers, S-100, melan-A, and HMB-45, but positive for neuroendocrine tumor markers, CD56, synaptophysin, and chromogranin A." (PMID 39192931, 2024). "All other markers tested were negative (pan-melanoma, HMB45, Melan A, keratin AE1/AE3, desmin, alpha smooth muscle actin, h-caldesmon, CD34, p16, CD117, DOG1, myogenin, CD10, estrogen receptor (ER), progesterone receptor (PR), PAX8, WT1, synaptophysin, chromogranin A, CD99 and PRAME))." (PMID 39196362, 2024). "Malignant melanoma, GIST, MPNST, sarcomatoid renal cell carcinoma, and malignant fibrous histiocytoma will be positive for vHMB-45, c-kit, S-100, RCC marker, and CD68, respectively, and will be negative for desmin, synaptophysin, inhibin, Melan-A, and calretinin." (PMID 25685588, 2015).